MUCL1 (mucin like 1)
Description:
May play a role as marker for the diagnosis of metastatic breast cancer.
Synonyms: SBEM
Tractability: Antibody: UniProt places it where antibodies can reach, with high confidence; its Gene Ontology location is reachable by antibodies, with high confidence; UniProt predicts a signal peptide or a membrane-spanning region. PROTAC: ubiquitination databases record sites on it; its protein half-life has been measured.
Gene: Protein-coding gene on chromosome 12 (54,830,518 to 54,896,008, forward strand). Ensembl gene ENSG00000172551.
Subcellular location: Secreted; Membrane
Pathways (Reactome):
Disease: Defective C1GALT1C1 causes TNPS; Defective GALNT12 causes CRCS1; Defective GALNT3 causes HFTC
Metabolism of proteins: O-linked glycosylation of mucins; Termination of O-glycan biosynthesis
Immune System: Dectin-2 family
Gene Ontology:
Molecular function: protein binding
Cellular component: Golgi lumen; plasma membrane; extracellular region; membrane
Genetic constraint (gnomAD): Loss-of-function variants: 11 observed, 9.87 expected, observed/expected ratio (o/e) 1.12, 90% interval 0.7 to 1.76. That is too few expected variants to judge how well the gene tolerates losing a copy. Missense variants: 144 observed, 117.58 expected, observed/expected ratio (o/e) 1.22, 90% interval 1.07 to 1.41. Synonymous variants: 48 observed, 42.26 expected, observed/expected ratio (o/e) 1.14, 90% interval 0.9 to 1.45.
Homologues: Orthologues: chimpanzee MUCL1 (99% identical), Drosophila melanogaster CG13965 (26% identical).
Diseases named in the same sentence as MUCL1 in open-access papers:
MUCL1 is named in the same sentence as 27 diseases in open-access papers, as found by Europe PMC text mining. Sharing a sentence is not in itself a finding about the gene and the disease. The quoted sentences say what the papers report.
breast carcinoma (20 papers, 2008 to 2025). "Our study reported a tumor cluster (C4 subgroup) with double-positive status of CD24 and MUCL1 in ER+ breast cancer, which was strongly associated with tumor metastasis." (PMID 41142825, 2025). "We also uncovered somatic mutations associated with the infiltration of CD24(+) MUCL1(+) cells, along with potential inhibitors for personalized treatment in ER+ breast cancer." (PMID 41142825, 2025). "Several years ago, mucin-like 1, the protein encoded by MUCL1 gene, was initially identified as a breast-specific gene expressed in more than 90% of breast cancer cell lines, developing an important role in the proliferation of these tumor cells." (PMID 31293564, 2019). "Mucins or mucin-like glycoproteins MUC5B and MUCL1 are often deregulated in cancer and are reported to have higher expression in breast cancer than normal tissue." (PMID 40597443, 2025). "This integrative approach, spanning molecular to imaging analyses, provides novel insights into both the biological drivers and clinical implications of MUCL1(+) CD24(+) cells in breast cancer progression." (PMID 41142825, 2025). "Through a comprehensive multi-omics strategy, we systematically characterized the biological and clinical significance of MUCL1+CD24+ cells in breast cancer, and we used multiplex immunohistochemistry to confirm the poor role of MUCL1+CD24+ cells." (PMID 41142825, 2025). "Our research provides pioneering insights into the pro-tumor effects and potential clinical applications of MUCL1(+) CD24 (+) cells in ER+ breast cancer." (PMID 41142825, 2025). "This investigation delineates a distinct C4 cellular subpopulation within ER+ breast cancer, identified via single-cell transcriptomic profiling and defined by the co-expression of MUCL1 and CD24." (PMID 41142825, 2025). "MUCL1 are identified as driver genes in subtype 1, which have been found to be critical markers of breast cancer." (PMID 38096269, 2023). "Previous studies found that MUCL1 is expressed by the majority of breast cancer cell lines (>90%) as it is recognized that mucins in general form the ductal surfaces of several organs, including the breast." (PMID 36672708, 2023). "Overexpression of MUCL1 mRNA was strongly correlated with higher tumor grade, lymph node positivity, and high recurrence and death rates in breast cancer patients." (PMID 36672708, 2023). "Mucin-like 1 (MUCL1), also known as SBEM, is a breast-specific gene that is associated with the occurrence, progression, prognosis, and chemotherapy response of breast cancer." (PMID 35847579, 2022). "A multiplex immunohistochemistry (mIHC) was performed on tumor specimens from ER+ breast cancer patients and based on the expression levels of C4-specific markers (MUCL1 and CD24); these cases were stratified into C4-high invasive and C4-low invasive subgroups." (PMID 41142825, 2025). "It was reported that knockdown of Mucin-like 1 (MUCL1) in HER2-amplified breast cancer resulted in FAK/Jun NH2-terminal kinase (JNK) signaling blockade and subsequent G1/S phase arrest, which was mediated by decreased cyclin D levels as well as increased p21 and p27 levels." (PMID 37749625, 2023). "We also found that some GRGs specifically associated with different tumor types are upregulated when compared to normal cells, as is the case of MUC21 in lung adenocarcinoma and GALNT6 and MUCL1 in non-TNBC breast cancer." (PMID 38384845, 2024). "Based on the GEO and TCGA databases, breast cancer-related genes analysis\showed that miR-186-5p was low-expressed, and SBEM (MUCL1) was high-expressed in the breast cancer group simultaneously, the low survival rate associated with high-expressed SBEM was plotted." (PMID 37477531, 2023). "MUC5B and MUCL1 (also known as Small Breast Epithelial Mucin/SBEM) have both been shown to drive invasion in vitro and are associated with poor survival and metastasis in breast cancer patients, although there are no reports on effects in ILC." (PMID 40597443, 2025).
asthma (1 paper, 2012). "This list included many genes with a purported role in regulation of the immune response in asthma: interleukins (IL2IL27 and IL33), chemokines (CXCL1CXCL17CCL5 and CCL27), mucins (MUC2MUC13 and MUCL1), TLR7 and NOS2, among others." (PMID 22713245, 2012).
colorectal cancer (1 paper, 2019). A primary or metastatic malignant neoplasm that affects the colon or rectum. "In addition, NRG1 is involved in constitutive signalling by aberrant PI3K in cancer, CSNK1A1L in signalling by WNT in cancer, and MUCL1 in defective GALNT12 causes colorectal cancer." (PMID 31797963, 2019).
dry eye (1 paper, 2022). "Finally, it has been found that MUCL1 is upregulated in dry eye patients, possibly as a compensatory response." (PMID 35409074, 2022).
lobular carcinomas (1 paper, 2026). "MUCL1 was expressed in 25% of cases in our cohort, enriched in apocrine and lobular carcinomas, and strongly correlated with AR, FOXA1, and GCDFP-15." (PMID 41987297, 2026).
stomach cancer (1 paper, 2017). "Lastly, a possible role of MUCL1 was explored, which showed an astounding increase in many stomach cancer histological subtypes." (PMID 28978023, 2017). "MUCL1 shows high expression in stomach cancer, especially in SIA NOS where up to 16.5-fold changes were observed." (PMID 28978023, 2017).
tumor (17 papers, 2004 to 2025). "This analysis revealed that most long-term survivors, over 12 months, had higher antibody titers against several tumor associated antigens, such as mucin proteins MUCL-1, MUC3B and the cancer testis antigen POTEE at baseline, than patients who survived for less than 1 year." (PMID 40887652, 2025). "Additionally, MUCL1 is recognized as an attractive tumor-associated antigen and a potential therapeutic target." (PMID 40838787, 2025). "It was noted that the ER+ Tumor group showed a significantly greater percentage of C0 MUCL1+ TCs and C2 ANKRD30A+ TCs in comparison to the Normal group." (PMID 40114930, 2025). "In this study, we identified a tumor subgroup characterized by high CD24 and MUCL1 expression, which was linked to poor prognosis and invasive behavior." (PMID 41142825, 2025). "Then, we verified the expressions of IGHG4, IGKC, APOD and MUCL1 at the protein level in tumor sections of clinical TNBC patients (HER2low, n = 5 vs. HER2neg, n = 5) by IF staining." (PMID 36998014, 2023). "Given the established role of somatic mutations in modulating cellular infiltration patterns, we propose that tumor-derived genetic alterations may similarly regulate MUCL1(+) CD24(+) cell expression within the tumor microenvironment." (PMID 41142825, 2025). "Additionally, in vivo and in vitro experiments need to be conducted to further explore the molecular function of the MUCL1(+) CD24(+) tumor cluster." (PMID 41142825, 2025). "Likewise, our data showed HER2low TNBC actively participated in activities with regard to tumor metabolism and growth pathways with MUCL1, PTN, SCGB2A2 and APOD highly expressed, revealing an increased metabolic and proliferative capacity contained." (PMID 36998014, 2023). "Furthermore, our result suggests that MUCL1 expression may be a surrogate marker for tumor response to OSI-027." (PMID 33858332, 2021). "In ER− patients, the result from the PPI networks of the tumours with the high expression of cytoplasmic CAIX demonstrated that two proteins, namely, GALNT6 and MUCL1, had significant interactions with each other." (PMID 39660488, 2024). "Strikingly, it showed that IGHG4 and IGKC were predominantly expressed in HER2neg TNBC group (in tumor tissues containing tumor cells and mesenchymal cells), whereas APOD and MUCL1 were highly expressed in HER2low group, which were consistent with the scRNA-seq data." (PMID 36998014, 2023). "Among the up-regulated genes in Luminal-Basal-type (vs. both Basal-single-type and Luminal-single-type) were present MUCL1, a known tumor suppressor gene, and CLCA2, a negative regulator of cancer cell migration and invasion." (PMID 35984580, 2022).
MUCL1 also shares sentences with these, for which no sentence is quoted: cancer (10 papers); triple-negative breast carcinoma (3); breast tumor (2); adenoma (1); brain cancer (1); colorectal adenocarcinoma (1); gastric adenocarcinoma (1); ichthyosis (1); keratoconus (1); laryngeal carcinoma (1); leukemia (1); liver cancer (1); lung adenocarcinoma (1); melanoma (1); multiple sclerosis (1); ovarian carcinoma (1); sarcoidosis (1); squamous cell carcinoma (1); thyroid cancer (1); uveal melanoma (1).